CLIC3 (CLIC family member 3)
Diseases named in the same sentence as CLIC3 in open-access papers (continued):
Sharing a sentence is not in itself a finding about the gene and the disease.
tumor (28 papers, 2012 to 2026). "In summary, we validated five highly expressed proteins as specific targets for different tumour mutational backgrounds: CLIC3, CRABP2, and GMDS for AKT1E17K/TRAF7 tumours, CD44 for KLF4K409Q/TRAF7 tumours and ANXA3 for NF2−/− tumours." (PMID 40562609, 2025). "Cox univariate and multivariate analyses showed that high CLIC3 mRNA expression was associated with tumor-specific survival in BC patients (P < 0.05)." (PMID 31934512, 2020). "Cox univariate analysis showed that invasiveness, N stage and systemic chemo were associated with overall survival; CLIC3 mRNA expression, gender and invasiveness were associated with tumor-specific survival." (PMID 31934512, 2020). "The multivariate analysis showed that invasiveness, N stage, and M stage were associated with overall survival; CLIC3 mRNA expression, gender, invasiveness, and N stage were associated with tumor-specific survival." (PMID 31934512, 2020). "The chloride intracellular channel protein 3 (CLIC3) is associated with tumor progression through its glutathione-dependent oxidoreductase activity." (PMID 29719590, 2018). "In contrast, chloride intracellular channel 3 (CLIC3) inhibits tumor proliferation by inhibiting NAT10 acetylation and reducing the ac4C level on p21 mRNA, revealing an internal balance mechanism within this pathway." (PMID 41446042, 2025). "In tumours with AKT1E17K/TRAF7 mutations, specific antibodies were available for four up-regulated proteins (CLIC3, CRABP2, GMDS, and Pyruvate carboxylase)." (PMID 40562609, 2025). "Consistent with the biological roles of CLIC3 in vitro, CLIC3 knockdown led to a significant decrease in growth and tumor weight of xenograft tumors." (PMID 38182571, 2024). "Previous studies have found that CLIC3 is closely related to the apoptosis and migration of tumor cells and plays an important role in the occurrence and development of tumors." (PMID 31934512, 2020). "Unexpectedly, expression level of CLIC3 was negatively correlated with pathological tumor depth: that is, the CLIC3-low samples showed deeper depth compared to the CLIC3-high samples." (PMID 32066374, 2020). "Further analysis revealed that patients with high CLIC3 mRNA expression had lower overall survival and tumor-specific survival." (PMID 31934512, 2020). "The results showed that patients with high CLIC3 mRNA expression had shorter tumor-specific survival time (P = 0.042)." (PMID 31934512, 2020). "The relationship between the expression of CLIC3 mRNA and tumor-specific survival in 165 BC patients was analyzed." (PMID 31934512, 2020). "CLIC3 is highly expressed in various tumors and promotes tumor development, leading to the poor prognosis of patients." (PMID 31934512, 2020). "It was further demonstrated that CLIC3 has a differential methylation profile in tumor samples compared to normal samples and was subsequently correlated with the increase in gene expression to increased protein expression in the same tumor samples." (PMID 32116799, 2020). "Cox univariate and multivariate analyses showed that CLIC3 was an independent factor influencing the tumor-specific survival of BC patients." (PMID 31934512, 2020). "In the presence of extracellular CLIC3, tumours had a more invasive phenotype, as assessed by the presence of DCIS-like structures with reduced sphericity (spherical related to in situ; nonspherical related to invasive)." (PMID 28198360, 2017). "This is further supported by our observations that CLIC3 is enriched at tumor invasive margins, and that its expression correlates with lymph node metastases and subsequent death from disseminated disease." (PMID 22197222, 2012). "Chloride intracellular channel 3 (CLIC3) protein has been reported to be associated with the progression of some tumors, whereas the specific mechanism of CLIC3 in tumor remains unclear." (PMID 38182571, 2024). "Moreover, it is of great significance to consider CLIC3 expression in tumor when targeting NAT10 for therapeutic purposes." (PMID 38182571, 2024).
tumor (continued). "Eight genes (SLC3A2, DARS2, DIP2C, PLOD1, RUNX2, ABCC9, AHNAK, and CLIC3) may be involved in the malignant transformation of tumours, and three genes (CHMP4C, POU5F1, and RAD9A) may have a protective effect in patients with tumours." (PMID 36685927, 2022). "Expression level of CLIC3 was found to be negatively correlated with pathological tumor depth." (PMID 32066374, 2020). "In fact, expression level of CLIC3 was negatively correlated with pathological tumor depth." (PMID 32066374, 2020). "This may contribute to the α5β1 dependence of CLIC3-driven invasiveness in both tumour and endothelial cells." (PMID 28198360, 2017). "Conversely, in tumors where Rab25 drives upregulation of CLIC3, lysosomally routed active integrins will be returned to the plasma membrane, thus avoiding degradation and enabling their continued signaling to drive tumor progression." (PMID 22197222, 2012). "Here we demonstrate a pathway for trafficking of activated α5β1 integrins in tumor cells that relies first on the ability of Rab25 to sort active heterodimers toward lysosomes, and then on CLIC3 to mediate the return of α5β1 from late endosomes/lysosomes to the cell surface." (PMID 22197222, 2012). "We considered whether these conflicts in the literature may, in part, be explained by Rab25's capacity to elevate CLIC3 levels in the tumor in question." (PMID 22197222, 2012). "While there is a slightly higher tumor mutational burden in EPAS1-altered tumors (9.9 vs. 4.9 mut/Mb), they are enriched in and associated with genes promoting immune evasion, including ARID5B, SPINT1, AAK1, CLIC3, SORT1, SASH1, and FGFR3, respectively (q < 0.001)." (PMID 36421334, 2022). "Hence, CLIC3 expression is enhanced in the stroma of different tumours." (PMID 28198360, 2017). "Moreover, CLIC3 was detected in the tumour stroma that also stained positively for αSMA and TGM2." (PMID 28198360, 2017). "Further more, research has implicated that an important protein CLIC3 (chloride intracellular channel protein 3) may determine whether or not Rab25 acts as a tumor promoter or suppressor." (PMID 25815277, 2015). "However, by driving CLIC3 expression, Rab25 increases tumor aggressiveness." (PMID 22197222, 2012). "To determine whether CLIC3 influences the ability of tumor cells to thrive in 3D microenvironments over a more prolonged period, we generated A2780-Rab25 lines that stably express small hairpin RNA (shRNA) duplexes to suppress CLIC3 levels." (PMID 22197222, 2012). "p < 0.0001) 26.4-fold increase in tumor (Mean ± SEM = 5.27 ± 0.1 log2TPM) compared to normal tissue (Mean ± SEM = 0.55 ± 0.14 log2TPM); CLIC3 mRNA exhibited a significant (Adj." (PMID 41465326, 2025). "CLIC3 inhibits NAT10 acetylation, reducing ac4C on p21 mRNA; p21 blocks cell cycle, inhibiting tumor proliferation." (PMID 41446042, 2025). "CLIC3, which belongs to a member of CLIC protein family, can act as a glutathione (GSH)-dependent oxidoreductase to promote tumor invasion via inhibiting the ability of TGM2." (PMID 38182571, 2024). "Through the HPA database, we found that three genes (ABCC9, AHNAK, and DIP2C) had low expression in patients with tumours, whereas eight genes (PLOD1, SLC3A2, RUNX2, RAD9A, CHMP4C, DARS2, CLIC3, and POU5F1) were highly expressed." (PMID 36685927, 2022). "While three genes (AHNAK, ABCC9, and DIP2C) were highly expressed in normal tissues, eight genes (CHMP4C, CLIC3, DARS2, PLOD1, POU5F1, RAD9A, RUNX2, SLC3A2) were highly expressed in tumour tissues." (PMID 36685927, 2022). "We subsequently investigated expression of PRDX1, FMNL, NCL, CLIC3, FLNA, PHB2, and FABP5 of 229 ESCC tumor tissues by TMA." (PMID 29683265, 2018). "For example, three chloride intracellular channel genes (CLIC3, CLIC4, and CLIC5) were down-regulated, while CLIC6 was up-regulated three-fold in tumor tissues." (PMID 24466154, 2014). "In the absence of CLIC3, RAB25 acts as a tumor suppressor, whereas in the presence of CLIC3, RAB25 increases tumor aggressiveness." (PMID 24216980, 2013).
tumor (continued). "In CAFs and tumor stroma, CLIC3 enhances ECM stiffness and angiogenesis in collaboration with the enzyme transglutaminase 2 (TGM2), driving the pro-invasive and pro-angiogenic functions of the tumor microenvironment." (PMID 41465326, 2025). "CLIC3 is a member of chloride intracellular channel (CLIC) protein family and may be related to tumor invasion." (PMID 39483475, 2024). "As previously reported that Rab25 acts as a tumor suppressor in the absence of CLIC3, whereas Rab25 increases tumor aggressiveness after driving CLIC3 expression." (PMID 38182571, 2024). "Through the HPA database, we found that three genes, namely ABCC9, AHNAK, and DIP2C, had low expression in patients with tumours, and eight other genes—PLOD1, SLC3A2, RUNX2, RAD9A, CHMP4C, DARS2, CLIC3, and POU5F1—were highly expressed in patients with tumours." (PMID 36685927, 2022). "It is suggested that in the presence of CLIC3, Rab25 acts as an oncogene, whereas, in the absence of CLIC3, Rab25 acts as a tumor suppressor." (PMID 28969096, 2017). "Therefore, we speculate that in tumors where CLIC3 is highly expressed, NAT10 will likely act as a tumor suppressor through interacting with CLIC3." (PMID 38182571, 2024). "Taken together, these data indicate that in the absence of CLIC3, Rab25 acts as a tumor suppressor." (PMID 22197222, 2012). "Of note, we demonstrated that the GST N-terminal domain of CLIC3 could bind the N-acetyltransferase domain of NAT10, which indicates that CLIC3 may act as a molecular chaperone and possibly alter the spatial conformation of NAT10, thereby changing the role of NAT10 in tumor progression." (PMID 38182571, 2024).
CLIC3 also shares sentences with these, for which no sentence is quoted: bipolar disorder (1 paper); colorectal cancer (1); COVID-19 (1); gallbladder carcinoma (1); meningioma (1); mucinous carcinoma (1); preeclampsia (1); pulmonary arterial hypertension (1).